FGF23 (fibroblast growth factor 23)
Diseases named in the same sentence as FGF23 in open-access papers (continued):
Sharing a sentence is not in itself a finding about the gene and the disease.
osteomalacia (continued). "Recently, burosumab, an antibody against FGF-23, was approved as a novel therapy for children and adults with X-linked hypophosphatemia and patients with tumor-induced osteomalacia." (PMID 36382755, 2022). "It has been shown that the elevated FGF23 production promoted mineralization defects leading to rickets and osteomalacia, contributing to bone loss by inhibiting the osteoblastic Wnt signaling pathway." (PMID 35622784, 2022). "Currently, an antibody against FGF23 (burosumab) is used for patients with FGF23-related ADHR/osteomalacia, such as those with X-linked hypophosphatemia." (PMID 35159314, 2022). "First identified two decades ago, mutations in the cleavage of FGF23 cause several inherited renal phosphate wasting diseases leading to rickets in children or osteomalacia in adults." (PMID 33191899, 2021). "FGF23 excess leads to several hypophosphatemic diseases featured by renal Pi wasting and rickets/osteomalacia, while deficient actions of FGF23 result in hyperphosphatemic tumoral calcinosis with enhanced renal Pi reabsorption." (PMID 34068220, 2021). "In humans, fibroblast growth factor 23, which is a causative factor of tumor-induced osteomalacia, is not only a paracrine and autocrine factor, but is also a physiological regulator of phosphate balance in normal serum." (PMID 32384911, 2020). "The overexpression of FGF23 is linked to hypophosphatemic rickets/osteomalacia, in contrast, a decrease in the action of FGF23 results in hyperphosphatemic calcinosis with high 1,25(OH)2D3 levels." (PMID 32204545, 2020). "X‐linked hypophosphatemic rickets (XLHR) represents the most common form of genetic hypophosphatemia and causes rickets and osteomalacia in children because of increased FGF23 secretion and renal phosphate wasting." (PMID 30352126, 2019). "Tumor-induced osteomalacia is a rare hypophosphatemic disease caused byunregulated production of fibroblast growth factor 23 by a tumor, therebyinducing renal phosphate wasting and inhibiting appropriate increase ofcalcitriol production." (PMID 31850815, 2019). "Laboratory abnormalities that are often associated with osteomalacia were observed in this case, including a reduction in serum phosphorus and an elevation in serum alkaline phosphatase and FGF23." (PMID 28193220, 2017). "Another interesting development is an anti-FGF23 antibody that has been tested for therapy of hypophosphatemic rickets/osteomalacia, where FGF23 excess was the cause for the disease." (PMID 26491212, 2015). "Osteomalacia arises in part because of a systemic deficiency in calcium and/or phosphate ions and the hormones responsible for their regulation—vitamin D and FGF23." (PMID 26347868, 2015). "In humans with normal renal function, excess FGF-23 causes rickets/osteomalacia and growth retardation, principally through lower serum phosphorus and suppressing 1,25D levels." (PMID 25208316, 2014). "In contrast to our patients with CKD-5D, in subjects with normal renal function excess, FGF-23 can cause rickets/osteomalacia through renal effects to reduce serum phosphorus and 1,25D levels." (PMID 25208316, 2014). "Abnormally elevated FGF-23 levels are seen in several pathological conditions and are associated with hypophosphataemia, low 1,25(OH)2D, urinary phosphate wasting and osteomalacia." (PMID 22984574, 2012). "This study demonstrates that the PAI‐1 antagonist TM5614 may be an effective treatment for vitamin D‐resistant rickets and osteomalacia caused by excessive production of FGF23." (PMID 38050660, 2024). "This indicates that the differential effect on FGF23 secondary to certain intravenous iron compounds may cause derangements in bone turnover and may have the potential to cause osteomalacia and fractures, especially after repeated infusions." (PMID 38347520, 2024).
osteomalacia (continued). "In addition to autosomal dominant hypophosphatemic rickets and tumor-induced osteomalacia, several types of hypophosphatemic rickets/osteomalacia have been shown to be caused by overexpression of FGF23." (PMID 36776964, 2023). "A recently developed medication, burosumab, might be considered to improve patients’ quality of life and to heal the underlying osteomalacia in patients with unresectable or recurrent FGF-23-producing PMTs." (PMID 37623022, 2023). "Thus, sustained and uncontrolled FGF23 production results in chronic hypophosphatemia, which ultimately causes muscle weakness, osteomalacia, bone pain, fractures, deformities, rickets, and growth impairment in children." (PMID 36943390, 2023). "Disorders associated with the excessive effects of FGF23 manifest hypophosphatemic rickets/osteomalacia characterized by renal Pi wasting and inappropriately normal or low levels of serum 1,25(OH)2D, and are collectively called FGF23-related hypophosphatemic rickets/osteomalacia." (PMID 36246908, 2022). "Osteomalacia is characterized by deficient bone matrix mineralization and may be caused by the excess amount of FGF-23 produced by a tumor." (PMID 35090436, 2022). "This includes various conditions such as tumor-induced osteomalacia caused by the overproduction of FGF23 due to phosphaturic mesenchymal tumors, hypophosphatemia associated with the intravenous administration of iron preparations, and genetic disorders, such as ADHR, XLH, ARHR1, ARHR2, and RNS." (PMID 36246908, 2022). "Complicated osteomalacia may be caused by the renal dysfunction and other pathology such as FGF23, other metals, organic substances, or chemical modification of cadmium." (PMID 25793409, 2015). "The prosthesis migration should be caused by osteomalacia due to FGF23-induced tumor." (PMID 23251177, 2012). "In addition, it has been shown that high FGF23 levels cause osteomalacia and rickets through phosphate and calcium metabolism and that iron replacement in pregnancy reverses the decrease in bone mineral density by decreasing FGF23 levels." (PMID 39045952, 2024). "The critical role of FGF23 in mineral ion homeostasis was first identified in human genetic and acquired rachitic disease, showing that an excess of FGF23 levels cause several types of hypophosphatemic rickets/osteomalacia, which are characterized by impaired mineralization of the bone matrix." (PMID 33669942, 2021). "This differs from the bone characteristics of individuals with normal kidney function, in whom large amounts of FGF23 result in low circulating phosphate levels, which in turn triggers severe osteomalacia and hypomineralized periosteocytic lesions." (PMID 41943820, 2026). "In a rickets/osteomalacia model, administration of an FGF23 neutralizing antibody in mice resulted in elevated serum phosphate levels and enhanced muscle function." (PMID 41278197, 2025). "It became available for clinical use in 2018 and was approved for insurance coverage in Japan in 2019 for the treatment of FGF23-related hypophosphatemic rickets and osteomalacia." (PMID 40978851, 2025). "Skeletal abnormalities seen with prolonged etidronate therapy include rickets and osteomalacia through a non-FGF23-mediated mechanism." (PMID 40176950, 2025). "Previous studies in mice and single reports in NF1 patients with osteomalacia have shown elevated serum FGF23 levels." (PMID 40133996, 2025). "Excessive FGF23 has been identified as a pivotal phosphaturic factor leading to renal phosphate wasting and the subsequent development of rickets and osteomalacia." (PMID 40439195, 2025). "After surgical excision of both lesions, we observed normalization of serum FGF23 levels and progressive resolution of osteomalacia." (PMID 38806758, 2024). "In contrast, XLH, formally known as vitamin D-resistant rickets or osteomalacia, is characterized by high FGF-23 levels and thus low 1.25 vitamin D and phosphate levels." (PMID 38542726, 2024).
osteomalacia (continued). "PMTs are characterised by paraneoplastic FGF23 overproduction, leading to renal phosphate wasting, chronic hypophosphatemia and, ultimately, osteomalacia." (PMID 39734682, 2024). "Hypophosphataemia and rickets/osteomalacia typically correlate with enhanced FGF23 levels in multiple hereditary disorders, thus providing clear evidence of a negative association between FGF23 and bone mineralization." (PMID 39054573, 2024). "We also systematically review the literature to discover possible correlations between osteomalacia, FGF23 production, and ovarian cancer." (PMID 38806758, 2024). "Surgical resection, with a complete excision, is the treatment of choice leading to the reduction of serum FGF23 levels and resolution of osteomalacia in most of the patients." (PMID 38806758, 2024). "They frequently elicit a clinical paraneoplastic syndrome consisting of hypophosphataemic hyperphosphaturic osteomalacia due to tumoural secretion of FGF23." (PMID 39506984, 2024). "Direct effects on FGF23 are seen in CSHS as well as X-linked hypophosphatemia and tumor-induced osteomalacia by suppressing renal phosphate reabsorption." (PMID 39416269, 2024). "Burosumab, a monoclonal antibody which inhibits FGF23, has been shown to increase serum phosphate, improve osteomalacia and enhance the healing of fractures in the medical management of TIO." (PMID 39734682, 2024). "Another most challenging etiological form of HBS is reported after the removal of a mesenchymal tumor with over production of Fibroblast Growth-Factor-23 (FGF-23) with phosphaturic effect and causing tumor-induced osteomalacia." (PMID 37296804, 2023). "Six weeks of dietary Pi supplementation exacerbated FGF23 production, hyperparathyroidism, renal Pi excretion, and osteomalacia." (PMID 37943605, 2023). "This approach completely restored Pi levels, bone growth, and mineralization, further demonstrating the major role of FGF23 and Pi bioavailability in the pathogenesis of rickets and osteomalacia." (PMID 37943605, 2023). "FGF23, a marker for tumor-induced osteomalacia, was slightly above normal; however, in many cases of this condition, this level is drastically elevated." (PMID 35145817, 2022). "While levels of FG23 are within the normal or low-normal range in the majority of osteomalacia-related diseases, they are inappropriately high by definition in FGF23-dependent disorders." (PMID 36499221, 2022). "Fibroblast growth factor 23 (FGF23)-related hypophosphatemic rickets/osteomalacia refers to a number of rare hereditary and acquired renal phosphate wasting disorders." (PMID 35769089, 2022). "The measurement of FGF23, when available, is important in the differential diagnosis of osteomalacia." (PMID 36499221, 2022). "A recent study showed that fibroblast growth factor 23 (FGF23) is a phosphatonin produced by bones, the excessive effects of which cause many types of hypophosphatemic rickets and osteomalacia." (PMID 34095182, 2021). "We showed that hepatic expression of the C-terminal tail of FGF23 corrected skeletal manifestations and osteomalacia in a XLH mouse model." (PMID 34705504, 2021). "Further investigations are warranted to assess to what extent iron supplementation can prevent FGF23-mediated hypophosphatemic rickets or osteomalacia." (PMID 33675347, 2021). "By contrast, phosphate was decreased in several affected family members while PTH and FGF23 remained in normal range and bone biopsies excluded osteomalacia." (PMID 34258505, 2021). "Given elevated urine phosphate, an oncologic osteomalacia was suspected and FGF23 was checked and was elevated at 548 (< 180) RU/mL." (PMID 33191899, 2021). "To date, there are only two identified causes of acquired FGF23-related hypophosphatemic osteomalacia: tumor-induced osteomalacia (TIO) and osteomalacia induced by the intravenous infusion of some forms of iron preparations." (PMID 34901334, 2021).
osteomalacia (continued). "For that reason, disruption of O-glycosylation must be involved in the development of intravenous iron preparation-induced FGF23-related osteomalacia." (PMID 34901334, 2021). "Plasma FGF23 is low or undetectable in patients with rickets/osteomalacia arising from nutritional vitamin D and dietary calcium deficiency, VDDR (types IA, IB, IIA and IIB, and III), or in cases of rickets secondary to renal Fanconi syndrome." (PMID 33660084, 2021). "Although the early conventional treatment is important for the improvement of bone microarchitecture, the persistence of osteomalacia implies seeking new therapeutic strategies, in particular anti-FGF23 approach, in order to optimize the treatment of XLH." (PMID 33681179, 2020). "XLH is caused by mutations in PHEX whose key consequences include elevations of fibroblast growth factor 23 (FGF23) causing renal phosphate losses and impairments of vitamin D activation with resultant hypophosphatemic rickets and osteomalacia." (PMID 32374835, 2020). "Autosomal dominant hypophosphatemia (ADH) causes rickets, osteomalacia, and taurodontism due to heterozygous mutations in FGF23, which inhibit the inactivation (cleavage) of the encoded protein, the hormone fibroblast growth factor 23 (FGF23)." (PMID 31834957, 2020). "A role for FGF23 in the pathogenesis of rickets and osteomalacia in TIO was identified shortly after its discovery, and was supported by the consistent appearance of bone abnormalities in FGF23-high diseases and animal models." (PMID 30808384, 2019). "Patients with TIO develop hypophosphatemic rickets/osteomalacia due to FGF23 excess and suffer from symptoms such as leg deformities, bone pain, skeletal muscle myopathy, and multiple fractures/pseudofractures." (PMID 30627598, 2019). "A new treatment for both XLH and tumor-induced osteomalacia with high FGF23 levels is the administration of an Anti-FGF23 Antibody (Burosumab, Crysvita®, Ultragenyx)." (PMID 30209646, 2018). "In one patient, with an FGF23 level of 110 RU/ml, an increased uptake of the somatostatin analog was observed due to tumor induced osteomalacia (TIO)." (PMID 30180816, 2018). "The pre-test probability for tumor-induced osteomalacia or inherited renal hypophosphatemia in a patient with aspecific complaints and a normal FGF23 level is low." (PMID 30180816, 2018). "The relative contribution of local accumulation of ASARM peptides and of OPN in the ECM versus the endocrine phosphaturic effect of Fgf23 to the osteomalacia observed in Hyp mice is currently unclear." (PMID 27035636, 2016). "In a study including two patients with FGF-23 mediated tumor induced osteomalacia, adjuvant therapy with cinacalcet led to increased plasma phosphate levels and allowed a substantial reduction of calcitriol and phosphate supplements." (PMID 24660072, 2014). "Among them, Fibroblast Growth Factor 23 (FGF23) is involved in various diseases, including autosomal dominant hypophosphatemic rickets/osteomalacia or tumor-induced hypophosphatemic rickets/osteomalacia." (PMID 25478250, 2014). "In summary, the multipronged approaches in this study demonstrated that inactivation of FAM20C in mice led to rickets/osteomalacia, along with altered levels of serum phosphate and FGF23." (PMID 22615579, 2012). "The serum level of fibroblast growth factor 23 is the most reliable marker for evaluating the treatment outcome of tumor-induced osteomalacia." (PMID 22747833, 2012). "An alternative explanation is that high demand for calcium due to massive bone formation induces hypocalcaemia, which gives rise to secondary hyperparathyroidism, which induces upregulation of Fgf23 and depletion of phosphate leading to osteomalacia." (PMID 22629419, 2012). "FGF23 was recently identified as an important factor involved in the development of hypophosphatemic rickets and osteomalacia." (PMID 23251177, 2012). "FGF-23 is the most reliable marker to evaluate the usefulness of any treatment for tumor-induced osteomalacia." (PMID 22747833, 2012).
osteomalacia (continued). "A recent report shows that overexpression of nuclear high molecular weight FGF2 isoform increases FGF23/FGFR/KLOTHO signaling, causing phosphate wasting and osteomalacia." (PMID 22629419, 2012). "In conclusion, we experienced a rare case of acute prosthesis migration after femoral replacement due to osteomalacia by FGF23-induced tumor." (PMID 23251177, 2012). "The most reliable marker for the detection of tumor-induced osteomalacia is FGF-23, which is a secreted peptide hormone overexpressed by the tumor in patients with tumor-induced osteomalacia." (PMID 22747833, 2012). "The administration of a high phosphate diet or performing injections of FGF23 neutralizing antibody can fully rescue the rickets phenotype but is only partially restored in osteomalacia." (PMID 22879941, 2012). "Dmp1−/− mice, like hyp mice (a well-studied hypophosphatemic rickets animal model), display abnormally high FGF23, low serum Pi, rickets and osteomalacia, which is a consequence of the defects in the osteocytes." (PMID 22879941, 2012). "Here, we presented a case of acute prosthesis migration after hemihip arthroplasty due to osteomalacia by FGF23-induced tumor." (PMID 23251177, 2012). "Our data and related publications demonstrate that FGF23 plays a pivotal role in osteomalacia-related side effects." (PMID 22629419, 2012). "The severe osteomalacia in Fgf23−/− mice, however, persisted, suggesting that a different mechanism is responsible for this mineralization defect." (PMID 22615584, 2012). "Fibroblast growth factor 23 (FGF23) was recently identified as an important factor involved in the development of hypophosphatemic rickets and osteomalacia." (PMID 23251177, 2012). "Here we used Dmp1 null mice, a hypophosphatemic rickets/osteomalacia model, combined with a metatarsal organ culture and an application of neutralizing fibroblast growth factor 23 (FGF-23) antibodies to gain insight into the roles of Pi in bone biology." (PMID 21542006, 2011). "FGF23 in turn decreases renal reabsorption of phosphate and suppresses renal production of 1,25(OH)2D, leading to rickets and growth impairment in children and osteomalacia in children and adults." (PMID 41777640, 2026). "Although there have been no previous studies in which IHC with PIDs was applied to bone tissue, the quantification of the FGF23 expression level in the bone was expected to be substantiated with this method, thus enabling us to elucidate the pathophysiology of alcoholic osteomalacia." (PMID 39963340, 2025). "Moreover, somatic mutations of the RAS gene in neoplasms can determine paraneoplastic production of FGF23 thus contributing to an osteomalacia-like bone phenotype." (PMID 40133996, 2025). "Before the quantification of FGF23 expression in bone biopsy samples from a patient with alcoholic osteomalacia, preliminary experiments to validate the ability of IHC with PIDs to differentiate ectopic excess FGF23 secretion from orthotopic excess FGF23 secretion were conducted." (PMID 39963340, 2025). "None of the participants were taking medications related to FGF23-associated hypophosphatemic rickets/osteomalacia (i.e., human anti-FGF23 monoclonal antibodies)." (PMID 41038963, 2025). "The keywords most frequently used by the authors were rickets (n = 188), FGF23 (n = 123), hypophosphataemia (n = 137), PHEX (n = 117), phosphate (n = 84), vitamin D (n = 82), osteomalacia (n = 81), X-linked hypophosphatemic rickets (n = 74) and burosumab (n = 60)." (PMID 41254716, 2025). "In conclusion, the oversecretion of FGF23 in a patient with alcoholic osteomalacia was demonstrated to be bone-derived, based on the analysis of bone samples using IHC with PIDs, which possesses much greater sensitivity and quantifiability than conventional IHC with DAB." (PMID 39963340, 2025).